PAX8 (paired box 8)
Diseases named in the same sentence as PAX8 in open-access papers (continued):
Sharing a sentence is not in itself a finding about the gene and the disease.
tumor (continued). "On immunostaining, the tumor cells were found to be negative for PAX8; however, they were positive for pan-CK and p63." (PMID 32164210, 2020). "All four MC-type HOV lines were negative for HNFB1 and WT1, and three out of four were negative for PAX8, while both HOV35 and its original tumor were positive for PAX8." (PMID 31248002, 2019). "The tumor cells were positive for cytokeratin MNF116, cytokeratin 7, TTF1, PAX8 and thyroglobulin." (PMID 31699114, 2019). "PAX8 is expressed in HGSC tumors derived from both the fallopian tube and ovarian surface epithelium (OSE), at least in murine models where the source of the tumor is experimentally derived." (PMID 30096791, 2018). "Immunohistochemically, the tumor is typically positive for PAX8 and negative for PAX2, TTF-1, and thyroglobulin; TTF-1 or thyroglobulin is required to rule out metastases from thyroid cancer." (PMID 29053609, 2017). "Our phenotypic characterization in PAX8 knockdown models is consistent with previous studies showing that PAX8 is involved in proliferation of EOC cells in vitro, and PAX8 knockdown impairs tumor formation in vivo." (PMID 29312534, 2017). "The transcription factor PAX8, shown to be hypermethylated in other tumor types, largely demonstrated a negative correlation to gene expression, where hypermethylation correlated with reduced expression." (PMID 26963385, 2016). "IHC revealed that the tumor diffusely expressed CD34, CD99, Bcl2, PAX8, NAB2, STAT6, and GRIA2." (PMID 26337721, 2015). "The functional significance of low PAX8 expression in MT-ECs is unclear, but our data suggest that PAX8 is not required for the development of this tumor type." (PMID 26132201, 2015). "Further, tumor cells had reduced CK8 and low PAX8 expression." (PMID 25971410, 2015). "By real-time RT–PCR, we observed that tumours negative for the PAX8-PPARγ rearrangement expressed lower levels of PPARγ mRNA than the NT." (PMID 15238980, 2004). "Furthermore, we used tSNE to visualize tumor cells and the expression levels of WFDC2 and PAX8." (PMID 39773329, 2025). "Various further tumor entities showed positive staining either for PAX8 or CDH16 but not for both." (PMID 39105782, 2024). "Therefore, PAX8 expression was analyzed in more than 17,000 tumor tissue samples from 149 different tumor types and subtypes as well as 76 non-neoplastic tissue categories by IHC in a tissue microarray (TMA) format in this study." (PMID 39105782, 2024). "Immunohistochemically, the tumor cells were strongly and diffusely positive for CK and CK7, moderately positive for Dog-1, and negative for vimentin, P63, P40, napsin A, thyroid transcription factor 1, chromogranin A, CD56, synaptophysin, S-100, SRY-related HMG-box 10, and PAX8." (PMID 36820581, 2023). "Immunohistochemistry corresponds to typical sex cord-stromal tumour profile (positivity for SF1, calretinin, inhibin, vimentin, often FOXL2; often oestrogen and progesterone receptor expression; and negativity or weak patchy staining for keratin, negativity for EMA, PAX8, and PAX2)." (PMID 36399188, 2023). "PDX models developed represented similar genomic (e.g., ARID1A, PIK3CA, KRAS etc.)and protein (PAX8, ARID1A, napsin A, racemase) profiles to the native patient tumor from which they were derived supporting use of these models as surrogates of the patient tumor." (PMID 37841875, 2023). "Indeed, it is important to note that SW1736 cells show high levels of PAX8, FOXE1 and CDH1, compared to KTC2, indicating ATC tumor heterogeneity that may influence the response to EZH2 modulation." (PMID 37175580, 2023).
tumor (continued). "The gene expression analysis of the full set of 11,003 samples from 33 TCGA tumor types identified three genes (MUC16, PAX8 and SOX17) that showed gene expression ranges of OSCA samples that did not overlap with the gene expression ranges of samples deriving from most of the other tumor types." (PMID 35954427, 2022). "Immunohistochemically, the staining results of tumor cells in the small intestine and kidney were consistent; the tumor cells were positive for CD3, CD56, granzyme B, TIA-1, and perforin, while negative for CD4, CD8, CD5, Desmin, CD34, CKpan, CD20, CD30, SMA, CD79ɑ, and PAX8." (PMID 36199094, 2022). "First, we categorized clustered data into tumor and stromal populations using a panel of markers for each (epithelial: AQP1, AQP2, EPCAM; endothelial: PLVAP, CD31, CD34; fibroblast: PDGFRα, PDGFRβ; immune: CD45; tumor cell: CXCR4, VIM, KRT18, PAX8, PAX2, CA9, CD10)." (PMID 34884982, 2021). "Immunostains showed the cells had patchy positivity for Pax‐8 and GATA‐3, and focal weak positivity for pancytokeratin and p63, while they were negative for TTF‐1, CK7, CK20, CA‐IX, and 34‐beta‐E‐12, compatible with a metastasis from a sarcomatoid neoplasm of renal origin." (PMID 32463173, 2020). "This could be particularly relevant in the development of HGSC because PAX8 is neither lost, mutated or overexpressed but is functionally retained possibly due to a selective advantage that it confers upon HGSC tumor cells." (PMID 31832016, 2019). "However, tumor growth in mice revealed undifferentiated carcinomas devoid of PAX8 expression, which were not similar to human HGSOCs." (PMID 29560094, 2018). "All tumours typed as negative for PAX8 had no positive nuclear staining." (PMID 24602166, 2014). "All non-tumour brain cells were PAX8-negative with one notable exception." (PMID 24602166, 2014). "In the present case, however, the tumor cells were negative for PAX8." (PMID 23044077, 2012). "PAX8 is also highly expressed in endometrium but does not undergo loss in EC, making PAX2 silencing a distinctive signature lesion of the endometrium and, as far as is known, unique among the PAX family as a tumor suppressor in the female reproductive tract or elsewhere." (PMID 40829174, 2025). "Notably, PAX8 was negative in the majority of the tumor and PD-L1 had a CPS of <5." (PMID 41043031, 2025). "Immunohistochemical analysis using the recommended minimum antibody panel (CAIX, TFE3, PAX8, HMB-45 and Melan-A, Cathepsin K, AMACR, CK-7, EMA) could be advised routinely for every case of RCC, regardless of the patient′s age and the microscopic features of the tumor." (PMID 35886994, 2022). "Moreover, we evaluated the expression of Ron isoforms in 3 of our newly developed HG-SOC PDX tumor models, which have also been immunohistochemically characterized for the expression of commonly used markers for HG-SOC subtype such as pan-cytokeratin (CK), PAX8 and WT1." (PMID 27551332, 2016). "Tumor cells were negative for CD34, TFE3, STAT6, ALK1, PAX8, AE1/3, and other epithelial, neural, and myogenic markers." (PMID 40948436, 2026). "Immunohistochemically, the tumor cells were diffusely positive for CAM5.2, AE1/AE3, and ER; focally positive for CD10, EMA, vimentin, WT1, CDX2, and p16; and negative for PAX8, CK7, calretinin, GATA3, Napsin A, and TTF1." (PMID 40959354, 2025). "The tumor was diffusely positive for CAM5.2, AE1/AE3, focally positive for PAX8, and negative for CK7, CD10, MART, TTF-1, Desmin, Calretinin, GATA3, ER, Inhibin, CK20 and EMA, with Ki-67 proliferative index > 80%." (PMID 39996894, 2025).
tumor (continued). "The tumor cells exhibited positivity for CK7 (partial), CK20, CDX2, and CAM5.2, while being negative for GCDFP15, S100, SOX10, GATA3, PAX8, and CK5/6." (PMID 40438862, 2025). "The tumor cells showed strong nuclear expression for GATA3 but no staining for TTF-1, CDX2, and PAX8, inferring primary breast origin." (PMID 40909459, 2025). "The tumor’s morphology and immunoprofile mimicked FATPWO, including PAX8 and CK7 negativity, and lacked specific molecular alterations." (PMID 40959354, 2025). "The tumor was positive for synaptophysin, CK-AE1/3, focal CDX-2, and focal chromogranin, while Müllerian markers (PAX8, WT-1, ER, and PR) were negative, supporting a diagnosis of primary ovarian LCNEC." (PMID 41149460, 2025). "On immunostaining, tumor cells were positive for GATA3, CD10, calretinin, TTF-1, and Pax-8 at various degrees, but were negative for ER." (PMID 39896229, 2025). "The tumor expresses TTF-1 and peculiarly estrogen and progesterone receptors but is negative for thyroglobulin and either negative or weakly positive for PAX8, suggesting a lack of definitive follicular cell differentiation." (PMID 40111709, 2025). "On immunohistochemical (IHC) staining, tumor cells showed patchy expression of CD56, but the tumor was negative for broad-spectrum keratins, PAX8, TTF1, thyroglobulin, calcitonin, HBME-3, CEA, PTH, GATA3, p63, SOX10, and S-100." (PMID 40277780, 2025). "Immuno-Histochemistry showed CD34 as negative in lining of ureter CAIX as positive in tumor, CD10 as positive in tumor, PAX8 as positive in tumor, CK7 as negative in tumor." (PMID 38952497, 2024). "Immunohistochemical stains were positive for PAX8, AE1/AE3, E-cadherin, CD10, and vimentin; the tumor was negative for CK7, CD117, racemase, ALK, and HMB45; the tumor showed focal, scattered staining for Melan-A and very weak cytoplasmic staining for CAIX." (PMID 39561576, 2024). "The immunohistochemical analysis revealed that the tumor was positive for CDX2, consistent with a gastrointestinal origin; the specimen was negative for CK7, CK20, and PAX-8, ruling out other common adenocarcinoma subtypes." (PMID 39434934, 2024). "On immunohistochemistry, the tumor cells were positive for S100P and SOX-10 and focally positive for HMB-45 and Melan A. Tumor cells were negative for CK, EMA, SMA, TTF1, PAX8, GATA3 and SALL4." (PMID 38509523, 2024). "The immunohistochemical analysis was essential in confirming the diagnosis, with the tumor showing positive staining for CDX2 and negative for CK7, CK20, and PAX-8." (PMID 39434934, 2024). "Immunophenotypically, the analysis of the tumor specimen revealed a strong expression of CDX2 and the absence of PAX8 expression, while only sporadic elements exhibited CK20 expression." (PMID 38732303, 2024). "The tumor cells were immunoreactive for pan-keratin (AE1/AE3) and PAX8, but no reactivity with KRT7, CA9 and TFE3." (PMID 37415400, 2024). "Immunohistochemistry staining showed the tumour was positive for AE1/3, CK7, GATA-3 and GCDFP-15; and was negative for CK20, PAX-8, CDX-2, WT-1, TTF-1, mammaglobin and BRAF V600E." (PMID 36871042, 2023). "We detected varying expression levels of the immunohistochemical markers CK20, PAX-8, and AMACR in the tumor cells of our patient, but not of CD117, CK7, CD10, and CA IX." (PMID 37098579, 2023). "Core biopsy of left chest wall nodule also revealed poorly differentiated LUAD with tumor cells positive for pan-keratin and TTF-1 and negative for ER, PR, CDX2, WT1, PAX-8, synaptophysin and chromogranin." (PMID 35546239, 2022). "Immunohistochemical stains showed the tumor cells to be positive for CD117, CD34 and CD10 and negative for ER, PR, CK7, PAX-8, pan-cytokeratin, EMA, S100, Melan-A, HMB45, SMA and CAIX." (PMID 36312876, 2022). "Immunohistochemistry showed that the tumor cells were positive for CK7, P63, P40, and CK5/6, and negative for TTF-1, PAX-8, S-100, SMA, Napsin A, HMB45, Syn, and CgA." (PMID 35346255, 2022).
tumor (continued). "The tumor showed the expression of cytokeratins, such as CK8-18 and AE1/AE3, and typical CD99 expression, whereas immunostaining for thyroglobulin, TTF1, PAX8, calcitonin, CK20, SOX10, ERG, SMA, and NUT was negative." (PMID 36129618, 2022). "Our result showed that the tumor tissue was positive in CK20, CDX-2, STAB2, and negative in CK7 and PAX8, which confirmed the appendix origin." (PMID 35721089, 2022). "Tumor cells were immunopositive for thyroid transcription factor 1 (TTF-1), Napsin-A and cytokeratin (CK)-7, and negative for paired box 8 (PAX-8), estrogen receptors (ER), progesterone receptor (PR) and CK20." (PMID 33853580, 2021). "Immunohistochemical analyses confirmed the tumor as derived from non-thyroidal tissues, as no immunoreactivity was noted for TTF1, PAX8, thyroglobulin, chromogranin A, calcitonin and CEA." (PMID 32519264, 2021). "Urine‐derived tubuloids were positive for paired‐box gene 8 (PAX8) and negative for tumour protein p63, confirming that these structures indeed consisted of kidney epithelium (PAX8+/TP63−) and not urothelium (PAX8−/TP63+)." (PMID 34165243, 2021). "In a series of 40 adolescent-onset PTC cases, two somatic DICER1 alterations were exclusively detected in each of the two PTC cases that lacked the molecular alterations typical of this tumor type (BRAF, HRAS, KRAS, NRAS, RET, and PAX8)." (PMID 33495912, 2021). "Immunohistochemically, the tumor cells are positive for CK7, CAIX, and PAX8, with absence of staining for CD117." (PMID 34680979, 2021). "Upon immunohistochemistry, these tumor cells expressed Ca19-9 and CK7, while staining negative for vimentin and Pax-8, thereby representing PDAC." (PMID 34059139, 2021). "Tumor cells were negative for GFAP, synaptophysin, keratins (Cam5.2, pancytokeratin), inhibin, carbonic anhydrase, PAX8, and D2-40." (PMID 34925233, 2021). "Immunohistochemically, the tumor cells are positive for CK7, CAIX, and PAX8, with absence of staining for CD117 and SDHB." (PMID 34680979, 2021). "The success of this model is underpinned by the fact that PAX8 is a marker of secretory cells in the FT, but not the ovaries and expressed in HGSC tumours in humans and mice." (PMID 32645943, 2020). "Immunohistochemically, the tumor cells expressed ER, PR, and GATA3; however, PAX8 was not expressed." (PMID 32164210, 2020). "This infiltrative thyroid tumor shows expression for PAX8 and cytokeratin 19 and can mimic PTC, but the tumor cells are negative for thyroglobulin and show negativity (clone 8G7G3/1) or focal positivity (clone SPT24) for TFF1." (PMID 32632840, 2020). "Neither hyperproliferation nor neoplasia was evident in the FT of LT mice, and the OSE-derived, LPT tumors also were PAX8-negative." (PMID 31772167, 2019). "Immunohistochemically, the tumour cells stained positive for EMA, CK5/6, CEA and p63 and were negative for PAX-8, RCC, CK7, SMA and S-100 protein." (PMID 28946910, 2017). "The tumour cells expressed CK5/6, EMA and p63 immunohistochemically but were negative for S100 protein, PAX-8, RCC and CK7." (PMID 28946910, 2017). "In our case, the tumor cells were positive for CK7, S-100, SOX10 and negative for PAX-8 and CD10, arguing against a metastatic clear cell RCC." (PMID 29041930, 2017). "Immunohistochemically (IHC), the tumor cells are positive for TFE3 and the renal tubular markers (PAX2 and PAX8), and completely negative for SMARCB1, an oncosuppressor protein." (PMID 27733182, 2016).
tumor (continued). "The immunophenotype (AE1/AE3-, vimentin+, PAX8-, alpha-inhibin+, Melan-A+, synaptophysin+ and NSE+) did not support a renal origin of the tumor." (PMID 27094262, 2016). "Immunostains were performed in which the viable adrenal cortical tumor cells expressed AE1/3 (weak, diffuse), melan A (strong, diffuse), and inhibin (moderate, diffuse), but were nonreactive for PAX8, CAIX, CD68, and CD163." (PMID 25108298, 2014). "The tumor cells were positive for HNF1-β and PAX-8, but negative for WT-1 and ER." (PMID 41479789, 2025). "Immunohistochemical analysis confirmed the positive expression of pankeratin, PAX8 and RCC in the tumour cells while showing negative results for SOX10, HMB45 and Melan A. A notably elevated proliferative index, as indicated by Ki‐67 labelling, was observed within the tumour." (PMID 39355743, 2024). "In tumor tissue, GATA-3, paired box 8 (PAX8), and CD10 were positive, and ER was negative." (PMID 39589956, 2024). "The tumor cells were positive for CA125 andHNF1β but negative for thyroglobulin, TTF-1 and PAX8." (PMID 39700333, 2024). "Tumoral cells showed positive staining for CD10, PAX8 and CA‐IX and they were negative for TTF1." (PMID 39031907, 2024). "Immunohistochemical analysis revealed the following results: Tumor cells were negative for Ckp, positive for desmin and actin, negative for myogenin, positive for MyoD1, and negative for CgA, S-100, Syn, h-caldesmon, SMA, Sox-10, Pax-8, and GATA3." (PMID 39139286, 2024). "All the five tumours in this study had a typical immunophenotype characterized by diffuse positivity for CK7 and negativity for CD117, and were also positive for PAX-8, E-cadherin, FH and SDHB, but negative for vimentin, CD10, P504s, CA9, CK20, TFE3, TFEB, HMB45, and ALK." (PMID 36816543, 2023). "In the same seromucinous tumor category, there was no uniform pattern in PAX2 and PAX8 expression." (PMID 35387670, 2022). "In the current study, all PRNRP cases exhibited a diffuse and strong expression of PAX8, CK7, and GATA3, whereas the expression of AMACR, CD10, and vimentin was either absent or only weak and focal, and the tumor cells were completely negative for CD117 and CAIX." (PMID 35936734, 2022). "Furthermore, the tumor cells were positive for cytokeratin (CK) 19; partially positive for thyroid transcription factor-1 (TTF-1); and negative for Pax-8, Napsin A, CDX-2, SATB2, and terminal deoxynucleotidyl transferase (TdT)." (PMID 33847622, 2021). "On IHC, tumor cells expressed RCC, PAX8, CD10 and Vimentin and were negative for CK7 and CK20." (PMID 34034720, 2021). "By immunohistochemistry, the tumor cells are often negative but can be focally positive for thyroglobulin; however, they are positive for TTF1, PAX8 (variable staining intensity), and estrogen and progesterone receptors and are negative for CK20 and calcitonin." (PMID 32632840, 2020). "However, on immunohistochemistry, the tumor cells showed immunoreactivity for Melan A and SMA and were negative for PAX-8, Pan-Cytokeratin, Myogenin, CD117, CD34, CK7, PAX-8 and HMB-45." (PMID 33344317, 2020). "Immunohistochemically, tumor cells were positive for cytokeratin (CK)-AE1/3, CK7, TTF-1, CEA, calcitonin, synaptophysin, and chromogranin A, but negative for CK20, Napsin A, Pax8, and p40." (PMID 29237502, 2017). "The tumor cells were positive for TTF-1, PAX8, Napsin-A and were negative for thyroglobulin." (PMID 27774331, 2016).